MRGPRE (MAS related GPR family member E)
Description:
G protein-coupled receptor for L-tryptophanocholate (Trp-CA), an amino-acid-conjugated bile acid produced by the microbiome, which regulates glucose homeostasis. Expressed in enteroendocrine L cells of the gut epithelium: Trp-CA binding causes a conformation change that triggers signaling via G(s) G protein, mediating activation of adenylate cyclase activity. In addition to G(s), MRGPRE also associates with beta-arrestin-1 (ARRB1), promoting phosphorylation of ALDOA. Both G(s) and beta-arrestin-1 signaling pathways improves glucose tolerance by enhancing GLP-1 secretion.
Synonyms: GPR167; MRGE; MGRF
Tractability: Small molecule: it belongs to a druggable protein family. Antibody: UniProt places it where antibodies can reach, with medium confidence; UniProt predicts a signal peptide or a membrane-spanning region; its Gene Ontology location is reachable by antibodies, with medium confidence.
Target class: Family A G protein-coupled receptor; Membrane receptor
Gene: Protein-coding gene on chromosome 11 (3,225,030 to 3,232,417, reverse strand). Ensembl gene ENSG00000184350.
Subcellular location: Cell membrane
Gene Ontology:
Molecular function: G protein-coupled bile acid receptor activity; protein binding; G protein-coupled receptor activity
Biological process: adenylate cyclase-activating G protein-coupled bile acid receptor signaling pathway; adenylate cyclase-activating G protein-coupled receptor signaling pathway; cell surface receptor signaling pathway; intracellular glucose homeostasis; positive regulation of insulin secretion involved in cellular response to glucose stimulus; G protein-coupled receptor signaling pathway; adenylate cyclase-modulating G protein-coupled receptor signaling pathway
Cellular component: plasma membrane; membrane
Genetic constraint (gnomAD): Missense variants: 466 observed, 396.54 expected, observed/expected ratio (o/e) 1.18, 90% interval 1.09 to 1.27. Synonymous variants: 229 observed, 184.88 expected, observed/expected ratio (o/e) 1.24, 90% interval 1.11 to 1.38.
Homologues: Orthologues: chimpanzee MRGPRE (99% identical), mouse Mrgpre (73% identical), guinea pig MRGPRE (73% identical), rat Mrgpre (72% identical). Paralogues in human: MRGPRG (34% identical), MRGPRX2 (34% identical), MRGPRX1 (33% identical), MRGPRX4 (33% identical), MRGPRD (32% identical), MRGPRX3 (31% identical), MRGPRF (30% identical), MAS1L (27% identical), MAS1 (25% identical), GPR152 (20% identical).
Diseases named in the same sentence as MRGPRE in open-access papers:
MRGPRE is named in the same sentence as 3 diseases in open-access papers, as found by Europe PMC text mining. Sharing a sentence is not in itself a finding about the gene and the disease. The quoted sentences say what the papers report.
airway hyperresponsiveness (1 paper, 2022). "Despite the fact that the role of MRGPRE is unknown, Mas-related G protein coupled receptors are involved in nociception homeostasis, bronchoconstriction, and airway hyperresponsiveness." (PMID 35033200, 2022).
Sleep apnea (1 paper, 2017). An intermittent cessation of airflow at the mouth and nose during sleep is known as sleep apnea. "Suggestive associations of symptoms of sleep apnea were observed with 11 rare variants (located in KANK2, LCN6, TRAF3, PLEK, HIF1A, SLC45A3, ERCC1/CD3EAP, MRGPRE, GRAMD4, TYW5, CST5)." (PMID 29093733, 2017).
MRGPRE also shares sentences with these, for which no sentence is quoted: migraine (2 papers).